PARP8 (poly(ADP-ribose) polymerase family member 8)
Description:
Mono-ADP-ribosyltransferase that mediates mono-ADP-ribosylation of target proteins.
Synonyms: ARTD16; FLJ21308; pART16
Tractability: Small molecule: a high-quality ligand is known. PROTAC: ubiquitination databases record sites on it; a small molecule that binds it is known.
Target class: Enzyme; Transferase
Gene: Protein-coding gene on chromosome 5 (50,665,899 to 50,846,519, forward strand). Ensembl gene ENSG00000151883.
Subcellular location (Human Protein Atlas): Nucleoplasm; Cytosol; Midbody ring
Pathways (Reactome):
Disease: Maturation of nucleoprotein
Metabolism: Nicotinate metabolism
Gene Ontology:
Molecular function: NAD+-protein mono-ADP-ribosyltransferase activity; NAD+-protein-cysteine ADP-ribosyltransferase activity; kinase binding; NAD+ poly-ADP-ribosyltransferase activity; protein serine/threonine kinase activator activity
Biological process: protein auto-ADP-ribosylation; endoplasmic reticulum unfolded protein response
Cellular component: endoplasmic reticulum tubular network; membrane; nuclear envelope
Genetic constraint (gnomAD): Loss-of-function variants: 35 observed, 76.59 expected, observed/expected ratio (o/e) 0.46, 90% interval 0.35 to 0.61. The upper end of that interval is the gene's LOEUF score, 0.61, which puts it in group 2 of 6, group 1 being the genes least tolerant of losing a copy. Missense variants: 643 observed, 777.3 expected, observed/expected ratio (o/e) 0.83, 90% interval 0.77 to 0.88. Synonymous variants: 299 observed, 284.73 expected, observed/expected ratio (o/e) 1.05, 90% interval 0.95 to 1.16.
Homologues: Orthologues: chimpanzee PARP8 (99% identical), macaque PARP8 (99% identical), rabbit PARP8 (98% identical), pig PARP8 (98% identical), rat Parp8 (97% identical), guinea pig PARP8 (96% identical), mouse Parp8 (96% identical), dog PARP8 (94% identical), tropical clawed frog parp8 (91% identical), zebrafish parp8 (73% identical). Paralogues in human: PARP6 (46% identical), PARP16 (9% identical).
Diseases named in the same sentence as PARP8 in open-access papers:
PARP8 is named in the same sentence as 8 diseases in open-access papers, as found by Europe PMC text mining. Sharing a sentence is not in itself a finding about the gene and the disease. The quoted sentences say what the papers report.
uveal melanoma (2 papers, 2024 to 2025). A melanoma derived from melanocytes of the uveal tract. "Recent studies indicate that PARP8 knockdown models in uveal melanoma cell lines decrease tumor cell proliferation and migration while promoting an immunosuppressive state of the tumor microenvironment, suggesting a pro-tumor role for PARP8." (PMID 41463260, 2025).
leukemia (1 paper, 2014). A malignant (clonal) hematologic disorder, involving hematopoietic stem cells and characterized by the presence of primitive or atypical myeloid or lymphoid cells in the bone marrow and the blood. "The candidates ATP2B2, PARP8 and TAS1R3 have previously not been functionally linked to leukemia." (PMID 24517546, 2014).
myopia (1 paper, 2021). "A heterozygous mutation in PARP8 was detected in a 25-year-old woman and her mother, both of whom had extreme myopia, with average spherical equivalent refractive error greater than −20 D and AL >29 mm." (PMID 34222226, 2021).
cancer (4 papers, 2021 to 2024). A tumor composed of atypical neoplastic, often pleomorphic cells that invade other tissues. "Furthermore, the subcellular localization, biological function, and mechanism of some members of the PARP family such as PARP8 remain unknown in cancer." (PMID 34976832, 2021). "Many of the upregulated genes, i.e., PARP8, ATP6, V1G3, NANOGNB, and CALB1, have been reported to be upregulated in various cancer cells." (PMID 36230929, 2022). "To date, a cellular function for PARP8 has not been established and no PARP8 inhibitors have been investigated for anti-cancer activity or clinically developed." (PMID 35096828, 2021).
tumor (3 papers, 2022 to 2025). "To further examine the role of PARP8 in tumor microenvironment, we analyzed the relationship between PARP8 and the expression of immune inhibitors." (PMID 37142279, 2023). "PARP7 and PARP8: PARP7 has also demonstrated a role in tumor cell growth." (PMID 41463260, 2025). "KDELR3 was mainly expressed in tumor cells, IDH2 was mainly expressed in endothelial cells, S100A6 was mainly expressed in photoreceptor cells, ITPA was mainly expressed in endothelial cells and tumor cells, PARP8 was mainly expressed in T cells, and APRC1B was mainly expressed in endothelial cells." (PMID 35242144, 2022). "Similarly, to date, the role of PARP8 in tumor progression has not been determined." (PMID 41463260, 2025).
PARP8 also shares sentences with these, for which no sentence is quoted: autism (1 paper); diabetes (1); Hepatic fibrosis (1).